RET (ret proto-oncogene)
Diseases named in the same sentence as RET in open-access papers (continued):
Sharing a sentence is not in itself a finding about the gene and the disease.
breast carcinoma (continued). "Therefore, in addition to the ~1.2% of breast cancer cases harboring RET alterations, breast cancer patients overexpressing RET-GFRα1 may also benefit from RET-targeted therapies." (PMID 35957881, 2022). "Thus, RET is actionable in endocrine-resistant ER+ breast cancers and these patients may benefit from combined inhibition of RET and ER pathway." (PMID 35957881, 2022). "In hormone positive breast cancer (BC), RET overexpression is described in less than 0.1% of cases and is involved in resistance to anti-hormonal therapies in BC cell lines." (PMID 33806299, 2021). "Moreover, a functional interaction between the RET and ER signalling pathways has been shown in breast cancer cell line studies: First, oestrogen stimulation seems to highly upregulate RET and GFRα mRNA, suggesting that RET and GFRα are direct target genes of oestrogen signalling." (PMID 30621641, 2019). "However, our results, derived from a large breast cancer patient cohort with annotated clinicopathological data, underline the uncertainty regarding the prognostic impact of RET expression on patient survival in breast cancer and stresses the importance of further research." (PMID 30621641, 2019). "A more comprehensive understanding of the effect of RET amplification on tumorigenesis and drug sensitivity as well as whether this alteration translates into increased mRNA and protein levels is needed, given its overall frequency in breast cancer." (PMID 30446652, 2018). "As genomic profiling cases may be biased toward more aggressive or refractory breast cancers and this cohort was restricted to cases with available ER status, the distribution of RET alterations may be skewed and limited in generalization to specific breast cancer subtypes." (PMID 30446652, 2018). "Interestingly, derivatives of the cytotoxic agent maytansine, a microtubule-interfering drug, conjugated to an anti-RET antibody show dose-dependent antitumor activity in RET expressing breast cancer xenograft models." (PMID 27602955, 2016). "In breast cancer, RET alterations occur in ~1.2% of cases, including CCDC6–RET, NCOA4–RET, RASGEF1A–RET, and ZNF485–RET fusions, or tandem duplications of exons 12–19." (PMID 41465145, 2025). "In ERα-positive breast cancer, researchers have reported that BRD4 triggers abundant transcription of target genes including RET by occupying ERα-controlled SEs." (PMID 38844984, 2024). "While RET is overexpressed in ERα-positive breast cancer, its activation stimulates the proliferation, survival, and dispersal of MCF-7 breast cancer cells." (PMID 39057095, 2024). "Together, our data suggest that RET is a driver of cell cycle progression at the G2-M phase of the cell cycle in combined CDK4/6i- and fulvestrant-resistant ER+ breast cancer cells." (PMID 39931212, 2024). "RET overexpression appears to contribute to resistance to combined CDK4/6i and endocrine therapy in ER+ breast cancer by promoting cell cycle progression at the mitotic phase." (PMID 39931212, 2024). "The very rare KIF5B-RET gene fusion, previously found only in a few breast cancer patients, can be treated with the FDA-approved targeted RET inhibitor selpercatinib." (PMID 38672643, 2024). "High RET mRNA expression significantly correlated with shorter OS (n=189, p=0.05, HR=1.92) in ER+, HER2- breast cancer patients treated with endocrine therapy." (PMID 39931212, 2024). "Effective treatment with selpercatinib was also documented in RET fusion-positive pulmonary large cell neuroendocrine carcinoma and ER+/HER2- breast cancer." (PMID 37627175, 2023). "Multiple potential mechanisms of endocrine resistance in breast cancer have been defined pre-clinically, including increased glial cell line-derived neurotrophic factor receptor (GFR)-coupled RET signalling." (PMID 39516358, 2023).
breast carcinoma (continued). "Treatment of breast cancer cell lines with recombinant IL6 reproduced this effect, identifying IL6 as the first ER-independent regulatory system governing RET expression in breast cancer." (PMID 36918928, 2023). "Taken together, these data suggest a role for RET expression and GDNF-mediated transcriptional programs in breast cancer disease progression, particularly in the aggressive Luminal B subtype." (PMID 36918928, 2023). "Six target genes (FGFR2, RET, ERBB4, SOX2, FN1, and MMP16) were analyzed across breast cancer studies using the cBioPortal to assess genomic alterations." (PMID 36601474, 2022). "In contrast to tight regulation in mammary epithelial cells, Stat3 signaling in breast cancer is dysregulated, and, although indirect, it is active downstream of ERBB2 and RET." (PMID 35044452, 2022). "Moreover, recent reports suggest that RET may regulate breast cancer metastases." (PMID 35957881, 2022). "Taken together, FGFR2, RET, and ERBB4 are potential targets of HON for overcoming ER+ breast cancer resistance to TAM." (PMID 36601474, 2022). "In conclusion, FGFR2, RET, ERBB4, MMP16, FN1, and SOX2 are potential targets of HON for overcoming TAM resistance in breast cancer." (PMID 36601474, 2022). "Focusing on breast cancer and melanoma models, the effect of the SCID mice plasma samples on the migratory and invasive properties of EMT6 and RET cells was assessed in vitro." (PMID 33707313, 2021). "Silencing of ST3GAL1 decreased GDNF-induced phosphorylation of RET, AKT and ERα, and reduced GDNF-mediated breast cancer cell proliferation." (PMID 33921986, 2021). "In breast cancer, HOXB5 enhanced cell growth and invasion partly through RET, ERBB2, EGFR, and ESR1." (PMID 34440097, 2021). "Extensive in vitro data unequivocally demonstrate that in breast cancer cell lines, GDNF promotes cell migration and survival in an RET-dependent manner, rendering cells insensitive to anticancer drugs targeting EsR or aromatase." (PMID 32993133, 2020). "The receptor tyrosine kinase RET (“REarranged during Transfection”) and its coreceptors of the GDNF family, including GFRα1, are frequently upregulated in ER+ breast cancer cases." (PMID 33233403, 2020). "To date, only the RET-ADCs Y078- DM1 and Y078-DM4 have been described as targeting a similar pathway to GFRA1-mediated inhibition in breast cancer." (PMID 29796165, 2018). "Since both RET and GFRA1 are naturally high in ER+ breast cancer cells, and since high expression of these factors appears to be established in part by ERα, there must be other causes of endocrine resistance, both in cell models and in vivo." (PMID 29608602, 2018). "Another study showed that through regulation of RET, the expression of TFAP2C decreased in luminal breast cancer." (PMID 30124166, 2018). "Based on initial detection in two index cases with RET fusions (RASGEF1A-RET and NCOA4-RET), 9693 breast cancers were evaluated for the presence of RET rearrangements as well as missense mutations and copy number changes." (PMID 30446652, 2018). "Here we investigated the efficacy of different small molecule RET kinase inhibitors, sunitinib, cabozantinib, NVP-BBT594 and NVP-AST487, and the potential of combining a RET inhibitor with the AI letrozole in ER+ breast cancers." (PMID 27602955, 2016). "Widening the scope beyond cancer types traditionally considered to be RET-driven, we also investigated the effect of SPP86 on RET- induced ERα phosphorylation and proliferation in MCF7 breast cancer cells." (PMID 25409876, 2014). "The effect of SPP86 on RET- induced phosphatidylinositide 3-kinases (PI3K)/Akt and MAPK pathway signaling and cell proliferation in MCF7 breast cancer cells was also investigated." (PMID 25409876, 2014). "A small molecule inhibitor with inhibitory activity towards RET, NVP-BBT594, has recently been shown to reverse resistance to aromatase inhibitors in breast cancer cells." (PMID 25409876, 2014).
breast carcinoma (continued). "Both RET and FAK inhibition impaired IL-6-induced migration and metastatic ability of breast cancer cells, and, conversely, when FAK is inhibited, RET-induced and IL-6-induced migration is abolished." (PMID 24467886, 2014). "RET is a receptor tyrosine kinase that mediates the proliferative and pro-survival effects of GDNF family growth factors in breast cancer." (PMID 21978374, 2011). "Notably, targeting RET with selpercatinib in combination with CDK4/6i inhibited the growth of CDK4/6i-resistant cell lines and resensitized ER+ breast cancer patient-derived organoids resistant to CDK4/6i." (PMID 39931212, 2024). "We first used the web-based tool Kaplan-Meier plotter to assess the correlation between RET mRNA expression and overall survival (OS) and relapse-free survival (RFS) in a cohort of ER+ breast cancer patients receiving endocrine treatment in the primary setting." (PMID 39931212, 2024). "While not yet in clinical trial for breast cancer, RET has recently been propsed as a novel target for ER fusion and mutant breast cancers." (PMID 39000231, 2024). "Furthermore, the RET inhibitor NVP-AST487, in combination with the AI letrozole, was also shown to be effective in inhibiting breast cancer cell line motility and growth." (PMID 39931212, 2024). "However, RET-directed TKIs seem to inhibit TNBC growth, providing preclinical evidence for the use of RET inhibitors in this subtype of breast carcinomas." (PMID 39211557, 2024). "Finally, we show that high mRNA levels of RET significantly correlated with shorter OS and RFS in patients with primary ER+ breast cancer who received any type of endocrine therapy." (PMID 39931212, 2024). "Since RET activates the RAS/MAPK and PI3K/AKT pathways in breast cancer cell lines, this might suggest that cell lines less dependent on these growth pathways will likely respond less to RET inhibition." (PMID 39931212, 2024). "While RET expression and function is significantly associated with ER positivity, RET overexpression has also been identified in the ER negative (ER−), triple negative (TN) and HER2-amplified breast cancer sub-groups." (PMID 36918928, 2023). "In these cell lines, it has been consistently demonstrated that treatment with estradiol (E2) induces transcription of multiple RET signaling system components, including RET, GFRA1, and ARTN, suggesting a regulatory mechanism for RET’s functions in breast cancer." (PMID 36918928, 2023). "RET has previously been shown to activate cytoskeletal remodeling and migration by binding and phosphorylating FAK (PTK2) and has been reported to activate similar mechanisms in breast cancer models." (PMID 36918928, 2023). "Alterations involving the RET oncogene have also been observed in patients with breast cancer, including canonical fusions and non-canonical missense mutations or amplifications." (PMID 37627175, 2023). "Based on these data, we propose that JMJD6 may be involved in predisposing cells to Tam insensitivity by decreasing ER, increasing RET expression and total ERK1 levels in ER+ breast cancer cells." (PMID 36419768, 2022). "Additionally, co-overexpression of RET-GFRα1 was inversely correlated with expression of basal markers and positively correlated with enhanced cell proliferation and survival of ER+ cells, suggesting that RET pathway activity may be a novel target in this breast cancer subtype." (PMID 35957881, 2022). "We also analyzed the relationship between the mRNA levels of FGFR2, ERBB4, RET, FN1, MMP16, and SOX2 and tumor stages in breast cancer using GEPIA and found that the levels of FGFR2 were significantly upregulated in stage I and remained stable across stages II–X." (PMID 36601474, 2022).
breast carcinoma (continued). "This has been completed in HCT-116 CRC cells and MCF7 breast cancer cells treated with conventional chemotherapies and in HCT-116, HT-29, and KM12C CRC cells treated with MEK, TRK, tyrosine kinase, RET, BRAF, PARP, PI3K, and GSK-3 inhibitors as well as Imipridones." (PMID 35205776, 2022). "At the same time, an elevated mRNA level of RET was detected only in 30–40% of breast cancer biopsies, and this parameter did not correlate with lymph nodes metastasis or lymphovascular invasion." (PMID 32993133, 2020). "The effects of inflammatory cytokine interleukin 6 (IL-6) on the migration of breast cancer cell lines were abolished in the presence of kinase inhibitors, although this interleukin does not activate RET directly." (PMID 32993133, 2020). "RET fusions were found in 116 cases of NSCLC, 14 cases of colorectal cancer, 2 cases of breast cancer, 1 case of thyroid cancer, and 3 cases of unknown primary cancer." (PMID 35582449, 2020). "At least in breast cancer cells, inflammatory mediators may upregulate GDNF expression, thus indirectly triggering RET signaling." (PMID 32993133, 2020). "While RET expression in pancreatic cancer has been consistently reported to correlate with poor survival results regarding survival in breast cancer are not entirely consistent and only a few reports using human tissue exist." (PMID 30621641, 2019). "Analysis of the RET genomic landscape has not been previously reported at this scale exclusively for breast cancer." (PMID 30446652, 2018). "RET genomic alterations were detected across all breast cancer subtypes although a majority were ER− (65%) or ERBB2 nonamplified (82%)." (PMID 30446652, 2018). "To extend this hypothesis to primary breast cancers, we sought to determine whether GDNF expression is normally low, such that it might limit RET pathway activation in most ER+ breast cancers." (PMID 29608602, 2018). "Multi-kinase inhibitors with activity against RET such as sorafenib, vandetanib, and others have been tested in clinical trials in unselected breast cancers with modest to no significant activity." (PMID 30446652, 2018). "Moreover, we also show that mRNA abundance of both RET and GFRA1 correlate with ESR1 across primary breast cancers, suggesting that RET and GFRA1 are direct targets of ERα signaling in primary patients as well." (PMID 29608602, 2018). "Although the role of RET expression in ER+ breast cancer has been under investigation, a comprehensive analysis of the presence and frequency of recurring RET genomic alterations, particularly RET rearrangements in breast cancer has not been reported." (PMID 30446652, 2018). "We reviewed the functional properties of the driver nodes found to have the highest impact in controlling the essential proteins; they are ERBB2, SRC, PDPK1, PRKDC, mTOR for breast cancer, ERBB2, AKT1, GSK3B, ABL1 in pancreatic cancer, and RET in ovarian cancer." (PMID 28871116, 2017). "We also identified 11 variants on genes known to predispose to other cancer types or cancer syndromes, like RET and AKT1, which have never been previously associated with breast cancer predisposition." (PMID 28569218, 2017). "It has also been demonstrated that ARTN promotion of the CSC population in ER- mammary carcinoma cells is equally efficacious in RET positive or RET negative cells." (PMID 26675549, 2016). "In addition, we detected previously identified RET fusions in new tumour indications, including a single CCDC6–RET fusion in colon adenocarcinoma and a single ERC1–RET fusion in breast cancer." (PMID 25204415, 2014). "However, no fusion transcripts involving the RET gene were identified in any of the ER+ breast cancer cell lines using three fusion callers (Fusioncatcher, STAR-fusion, and Arriba)." (PMID 39931212, 2024). "In addition, patients with breast cancer with low mRNA levels of RET, MMP16, FN1, and SOX2 had better RFS, but this was not significant in the opposite groups (p > 0.05)." (PMID 36601474, 2022).
breast carcinoma (continued). "Importantly, our data suggests that RET expression has no impact on overall survival and thus is not a prognostic factor in human breast cancer." (PMID 30621641, 2019). "Importantly, RET expression had no significant impact on overall survival and is thus not a prognostic factor in human breast cancer in our collective (p = 0.79)." (PMID 30621641, 2019). "In summary, recurrent canonical and noncanonical RET alterations are observed in breast cancer." (PMID 30446652, 2018). "Similarly, in breast cancer, RET-targeting TKIs have not shown significant benefit, although previous studies have not specifically focused on RET-positive tumors." (PMID 30666215, 2018). "Further, it has been recently demonstrated that RET expression and activation may also be physiologically relevant in triple negative (negative for ER, progesterone and HER2 receptor expression) and HER2 positive breast cancers." (PMID 27602955, 2016). "In summary, the data presented support the hypothesis that RET inhibitors, such as NVP-AST487, could both impair primary tumor growth and tumor dissemination, thereby providing a potential therapeutic advantage when used in combination with AIs in post-menopausal ER+ breast cancers." (PMID 27602955, 2016). "However, the successful approval of TKIs to treat ROS1-, RET-, NTRK1-, PDGFR-α, and AXL-rearranged NSCLC is vitally important as it sets the example for approval of TKIs to treat the same RTK-rearranged common epithelial tumors such as colon, gastric, and breast cancers." (PMID 24744988, 2014).